CDKN2A (cyclin dependent kinase inhibitor 2A)
Diseases named in the same sentence as CDKN2A in open-access papers (continued):
Sharing a sentence is not in itself a finding about the gene and the disease.
melanoma (continued). "In the inherited form of melanoma, the primary genes involved are CDKN2A and MC1R." (PMID 32169117, 2020). "We also discuss the impact of CDKN2A on the response of melanoma patients to current therapies." (PMID 33076392, 2020). "Recently, it has been reported that lack of Cdkn2a in V600E BRAF mutated melanocytes in rodents is associated with rare progression to melanoma." (PMID 32556513, 2020). "Because melanoma patients commonly harbor genetic alterations in BRAF, NRAS, CDKN2A, or NF1 genes that contribute to tumor progression, we examined potential associations between these genetic alterations and IRAK-M levels in melanoma cell lines and patient samples." (PMID 32533049, 2020). "Single nucleotide polymorphisms p.R24P, p.M53I, p.G101W, p.V126D, and p.A148T in the CDKN2A (HGNC ID: 1787) gene have been associated with the development of melanoma in different populations; however, this association has not been studied in Colombia." (PMID 33102592, 2020). "In contrast, CDKN2A promoter hypermethylation occurs most frequently in NRAS-mutant melanoma (87.7%) and is less common in melanoma with BRAF mutations (67.0% with CDKN2A promoter methylation) and in melanomas with NF1 mutations (77.3% showing CDKN2A promoter methylation)." (PMID 33076392, 2020). "Polymorphisms in genes involved in DNA repair (POLN, PRKDC), immune regulation (IL9), and apoptosis (BCL7A, BCL2L1) have also been associated with increased melanoma risk, and in some instances, these polymorphisms (IL9 and BCL7A) have stronger risks in CDKN2A-positive families." (PMID 33076392, 2020). "Based on genetic linkage analyses, the Cdkn2ab gene was proposed as the critical component of the tumour suppressor R locus (so named due to 55% amino acid homology with the human tumour suppressor genes CDKN2A and CDKN2B that are frequently mutated in melanoma)." (PMID 32652526, 2020). "The deficiency of cyclin-dependent kinase inhibitor 2A (Cdkn2a, Ink4a) gene, whose inactivtion is associated with melanoma-pancreatic cancer syndrome in human, would not couse the spontaneous pancreatic cancer." (PMID 32047562, 2020). "As mutations in high-susceptibility genes greatly increase risk of melanoma development, individuals carrying CDKN2A, CDK4, BAP1, POT1, or MITF mutations should be educated on the importance of melanoma prevention and early detection and should undergo regular medical skin examination." (PMID 31717496, 2019). "The increased expression of EZH2 in melanoma results in the hyper-activation of PRC2 with consequent tri-methylation of H3K27, silencing of CDKN2A and CDKN1A tumor suppressor genes, and is associated with thicker primary melanomas, aggressive metastatic behavior, and a poor prognosis." (PMID 31861757, 2019). "This protein is rendered non-functional in suppressing superoxide and melanoma cell proliferation when CDKN2A is mutated." (PMID 31417903, 2019). "The pathogenic variants detected in the pre-treatment scalp melanoma included the BRAF-V600E mutation (BRAF c.1799 T > A, p.V600E), amplification of BRAF located on chromosome 7q34, and loss of the tumor suppressor gene CDKN2A located on chromosome 9p21.3." (PMID 31703593, 2019). "The frequency of CDKN2A mutation is higher in MPM patients with a family history of melanoma compared to those without (35–47% vs. 3.2–15%, respectively)." (PMID 31382929, 2019). "This variant co-segregated with cancer in a family with 14 melanoma cases who were not carriers of germline mutations in the two known melanoma genes, CDKN2A and CDK4." (PMID 30453575, 2018). "Currently the only established high penetrance familial melanoma genes are CDKN2A and CDK4." (PMID 29523635, 2018).
melanoma (continued). "BRAF mutation and CDKN2A inactivation have been found associated with MITF amplification in melanoma cell lines, but such a correlation was not confirmed in our series." (PMID 29492214, 2018). "CDKN2A/CDK4 were the first high- penetrance melanoma genes identified." (PMID 29774366, 2018). "The aim of the study was to evaluate any possible correlation between mutations in main growth-controlling genes (BRAF, NRAS, CDKN2A) and copy number variations in frequently amplified candidate genes (MITF, EGFR, CCND1, cMET, and cKIT) during melanoma initiation and progression." (PMID 29492214, 2018). "We have also investigated the possible protective role of oral administration of PL in patients at risk of malignant melanoma (MM) and evaluated the influence of PL in the interaction between MC1R polymorphisms and the cyclin-dependent kinase (CDK) inhibitor 2A gene (CDKN2A) status with MED." (PMID 29998107, 2018). "It is unclear whether other common variants that have been associated with melanoma, particularly other pigmentation genes, such as SLC45A2, TYR or TYRP-1, may also exhibit a similar modifying effect CDKN2A penetrance similar to MC1R." (PMID 29774366, 2018). "For melanoma cell lines, the same lack of correlation between gene amplification and CDKN2A mutational status was observed: 14/19 (74%) CDKN2A-mutated and 10/13 (77%) CDKN2A-wild-type cell lines were found to carry amplification in at least one gene locus." (PMID 29492214, 2018). "Considering the extremely rare coexistence of MPM and OCA, we decided to analyze in the two indexes affected by both conditions, over CDKN2A and CDK4 alterations, a pattern of other genes involved in melanoma predisposition and pathogenesis, in skin/hair pigmentation and in immune pathways." (PMID 27776349, 2017). "CDKN2A loss-of-function mutations are associated with a high risk of melanoma in humans but not for other tumor forms." (PMID 28388616, 2017). "However, ultraviolet radiation therapy (UVR) treatment in these animals induced melanoma with long latency: interestingly, CDKN2A was found to be deleted in developing tumors." (PMID 29156643, 2017). "Notably MTAP is lost in ~25% of melanomas due to its proximity to CDKN2A, a commonly deleted tumour suppressor gene, exposing this as a potentially therapeutically relevant vulnerability in melanoma." (PMID 28097822, 2017). "Additionally, Lucanthone and Podofilox were identified as having potential effects on melanoma through CDKN2A and MAP kinase, respectively." (PMID 37133296, 2017). "However, there is a strong link between CDKN2A and melanocyte biology as mutations inactivating the ARF protein are a major risk factor for familial forms of melanoma in humans." (PMID 28388616, 2017).
melanoma (continued). "During our analysis of the CDKN2a locus in malignant melanoma we discovered that upregulation of the pro-survival gene MCL-1 was associated with loss of ARF, a relatively common occurrence in melanoma, providing some explanation for the characteristically chemo-resistant behavior of most melanomas." (PMID 27846237, 2016). "The acquisition of TERT promoter mutation in BRAF or NRAS mutated melanoma probably allows the re-expression of TERT leading to the immortalization process on path to melanoma development, together with other alterations such as inactivation of cyclin-dependent kinase inhibitor 2A (CDKN2A)." (PMID 27449293, 2016). "The patient has no reported family history of melanoma and is not carrier of the high-risk genes CDKN2A and CDK4." (PMID 27022491, 2016). "In contrast to these studies, putative loss-of-function germline variants in EDNRB were associated with cyclin-dependent kinase inhibitor 2A, CDKN2A, variants in familial melanoma cases in a French population, but not in an Italian population." (PMID 27148356, 2016). "Additionally, we used data from 60 primary melanoma tumors that had been previously screened for deletions at the CDKN2A/B locus." (PMID 26909863, 2016). "Several genes have been implicated in the development of melanoma: genes involved in the MAPK pathway (RAS and BRAF, the most frequent mutations), CDKN2A [a cyclin-dependent kinase (CDK) gene] genes that are associated with nevi and pigmentation traits, such as MTAP, MC1R, and TYR." (PMID 27833586, 2016). "Cohort B comprised 5 individuals from the same family as in Cohort A with CDKN2A/p16 mutations, but with no history of melanoma at the time of this study." (PMID 26694476, 2015). "In addition, activity of CDK4/6 is frequently up-regulated by deletion of CDKN2A (p16INK4a) or increased expression of cyclin D1 in melanoma." (PMID 26295265, 2015). "Age at first melanoma in CDKN2A mutation carriers compared to age of first melanoma in individuals with melanoma and no CDKN2A mutation." (PMID 25803691, 2015). "To-date, no melanoma families have been identified that carry missense mutations in exon 1β, however, very recent studies have shown that p14-specific alterations in CDKN2A exon 2 impair the ability of p14 to control superoxide levels and suppress growth of melanoma cells in vivo." (PMID 25803691, 2015). "Among CDKN2A-mutation carriers, the methylation mean was 0.63% (ranging from 0 up to 1.5%), hereditary melanoma patients without CDKN2A-mutations showed a mean of 0.52% (0–3.0%), and sporadic melanoma patients presented a mean of 0.35% (0–1.5%)." (PMID 26106605, 2015). "To date there has been no large study of genetic alterations in Danish high-risk melanoma cases, and we were intrigued by a clinical observation of an apparently low frequency of CDKN2A mutations when testing was conducted in a clinical genetic setting." (PMID 25803691, 2015). "Mutations in the CDKN2A and CDK4 genes predispose to melanoma." (PMID 25780468, 2014). "To do so we analyzed co-cultured melanocyte-keratinocyte systems derived from two siblings belonging to two melanoma prone families with a founder CDKN2A mutation and/or carrying non-functional MC1R alleles to compare global gene expression profiles." (PMID 24742402, 2014). "CDKN2A locus is frequently deleted in melanoma of all primary subtypes." (PMID 24743024, 2014). "We have previously reported that the penetrance of CDKN2A mutations in population-ascertained families is similar in the UK and Australia; mutation carriers appeared to have the same cumulative risk of melanoma irrespective of ambient UV irradiance." (PMID 25780468, 2014). "Additionally, a small number of melanoma pedigrees have been found to carry mutations of the CDK4 gene, at the binding site for the CDKN2A gene product." (PMID 25780468, 2014).
melanoma (continued). "The strengths of our study include a rich collection of genetic, exposure, clinical, and pigmentation data in melanoma-prone families with and without known CDKN2A mutations." (PMID 23990928, 2013). "In this exploratory analysis, we evaluated TL in blood in relation to CMM, CDKN2A germline mutation status, and CMM risk factors in 53 melanoma-prone families with and without CDKN2A mutations." (PMID 23990928, 2013). "A CDKN2A knockout mouse model has shown that melanoma develops after a single neonatal UV dose, suggesting that alterations in the CDKN2A may play an important role in the UV-induced development of melanoma." (PMID 23303275, 2013). "Mutations in the cell cycle gene CDKN2A (gene or mono-allelic loss at the locus) were connected with high risk of melanoma but results are not clear." (PMID 22759494, 2012). "We found deletion (reduced gene dosage) at the CDKN2A locus to be common in primary melanoma." (PMID 20140953, 2010). "This study presents supportive evidence that CDKN2B, P14ARF, and CDKN2A may all play a tumor suppressor role in melanoma progression." (PMID 20140953, 2010). "Interestingly, MTAP and CDKN2A are frequently homozygously co-deleted otherwise, inactivated in tumor cells including melanoma, resulting in higher intra and extracellular MTA levels." (PMID 20529342, 2010). "An American study showed that the mean tumour thickness of prospectively identified melanomas (i.e., by means of screening activities) was 0.46 mm and of those identified prior to the study 1.03 mm (in 17 CDKN2A positive families) thus indirectly illustrating the efficacy of screening." (PMID 24281082, 2010). "Melanomas also harbor mutations that promote the malignant phenotype, such as in BRAF, CDKN2A, PTEN, CTNNB1, NRAS, PIK3CA and KIT, but except for BRAF (∼50%) and common loss of CDKN2A, these mutations exist in a minor portion of melanoma specimens (10% or less)." (PMID 19234609, 2009). "The present study has shown a high prevalence of CDKN2A mutations affecting p16INK4A in Slovenian population of familial melanoma patients (37%) and an absence of p14ARF or CDK4 mutations." (PMID 18803811, 2008).
melanoma (continued). "Although the CDKN2A gene has been shown to be the major melanoma predisposing gene, there remains a significant proportion of melanoma kindreds linked to 9p21 in which germline mutations of CDKN2A have not been identified through direct exon sequencing." (PMID 18612309, 2008). "In all, 20% of melanoma families were found to harbour genetic alterations at the CDKN2A/ARF gene." (PMID 15928671, 2005). "Taken together with the data reported herein, it appears that in over 60 Ashkenazi Jewish melanoma families, no germline alteration in CDKN2A/ARF and CDK4 loci underlie the apparent predisposition." (PMID 15928671, 2005). "Physical interaction between CDKN2A/p16 and CDK4 proteins regulates the cell cycle progression through the G1 phase and dysfunction of these proteins by gene mutation is implicated in genetic predisposition to melanoma." (PMID 11556834, 2001). "Our results, obtained in a heterogeneous group of families, support the view that inactivating mutations of CDKN2A contribute to melanoma susceptibility more than activating mutations of CDK4 and that other genetic factors must be responsible for melanoma clustering in a high proportion of families." (PMID 11556834, 2001). "Furthermore, our results are consistent with prior studies reporting robust ddPCR performance in cancer detection; for instance, an investigation into CDKN2A copy number variations in 57 FFPE melanoma samples yielded a sensitivity of 94.4% and a specificity of 90.0%." (PMID 40725150, 2025). "Interestingly, the probability to found CDKN2A mutations is about 1% in sporadic melanoma patients without personal and/or familial history of melanoma." (PMID 39609109, 2025). "A subsequent GWAS, carried out on 35 Swedish families with no CDKN2A mutations, detected a strong association with the region Chr17p12–p11 suggesting that this locus may contain genes involved in melanoma susceptibility, at least in Sweden." (PMID 40869905, 2025). "Additionally, the most common molecular aberration after loss of 3p21 was heterozygous loss of the CDKN2A locus, which, unlike homozygous loss, has not been associated with melanoma." (PMID 39976080, 2025). "Further, while we chose SK-MEL-5 cells as a representative of melanoma cells due to their BRAF mutation and cellular morphology, a difference between this cell line and other established lines is that the donor was significantly younger (24 years old) and has a CDKN2A mutation." (PMID 40428399, 2025). "Dedicated specialist clinics can offer an extended surveillance programme for individuals with increased melanoma risk, such as those with CDKN2A GPVs (a major melanoma susceptibility gene) or with a personal history of multiple early onset melanomas (where a melanoma gene panel is negative)." (PMID 40350252, 2025). "The genetic landscape of melanoma includes rare high-penetrance genes, such as CDKN2A, which are implicated in some familial cases, as well as more common pigmentation-related genes, such as MC1R, that increase the susceptibility of fair-skinned individuals to melanoma." (PMID 39941357, 2025).